RN7SL763P (RNA, 7SL, cytoplasmic 763, pseudogene)
Gene: Miscellaneous RNA gene on chromosome 9 (39,886,861 to 39,887,144, reverse strand). Ensembl gene ENSG00000277774.
Homologues: Orthologues: chimpanzee Metazoa_SRP (99% identical), macaque Metazoa_SRP (94% identical). Paralogues in human: RN7SL544P (100% identical), RN7SL787P (99% identical), RN7SL565P (99% identical), RN7SL722P (99% identical), RN7SL52P (99% identical), RN7SL205P (97% identical), RN7SL1 (81% identical), RN7SL2 (81% identical), RN7SL3 (81% identical), RN7SL322P (80% identical), RN7SL230P (80% identical), RN7SL709P (80% identical), and 706 more.